PPARG (peroxisome proliferator activated receptor gamma)
Diseases named in the same sentence as PPARG in open-access papers (continued):
Sharing a sentence is not in itself a finding about the gene and the disease.
Rotavirus infection (2 papers, 2016 to 2020). Infection with any of the rotaviruses. "A thorough understanding of the mechanisms supporting rotavirus infection is vital for comprehending better the inhibitory effect based on PPARγ agonists and antioxidants." (PMID 27382365, 2016). "In the current paper, we study the in vivo and in vitro effect of PGZ and other PPARγ agonist on rotavirus infection of small intestinal villus cells." (PMID 27382365, 2016). "It is proposed that rotavirus infection is sensitive to the expression of genes regulated by transcription factors binding to PPARγ response elements (PPREs) and ATRA response elements (RAREs)." (PMID 27382365, 2016). "The PGZ inhibitory effect through PPARγ activation gives us a better insight into the host cell response to rotavirus infection and the mechanisms involved in its pathogenesis." (PMID 27382365, 2016). "Furthermore, the inhibition of mtROS, at least partly through peroxisome proliferator-activated receptor gamma (PPARγ) activation, played a beneficial role in the reduction of rotavirus infection." (PMID 32922385, 2020). "In conclusion, the results reported here provide evidence that PPARγ agonists and ATRA exert an inhibitory effect on mouse intestinal villi infected in vivo with ECwt, causing a significant reduction of infectious virions and decreasing some of the cellular proteins involved in rotavirus infection." (PMID 27382365, 2016). "The effects of PPARγ agonists and ATRA on rotavirus infection in a synchronous system consisting of small intestinal villi isolated from mice suggest that genes controlled by PPREs and RAREs are involved in the viral cycle inhibition." (PMID 27382365, 2016). "PPARγ activation has been shown to block TNF-α production, while NAC suppresses TNF-induced NF-κB activation and inhibits rotavirus infection." (PMID 27382365, 2016). "However the precise mechanisms of how PPARγ agonist- and ATRA-induced genes regulate rotavirus infection cycle are not completely understood and deserve further research." (PMID 27382365, 2016). "Activation of PPARγ by thiazolidinediones (TZDs) has been shown to interfere with the NF-κB signaling cascade, which has been reported to mediate COX-2 expression while inhibition of COX-2 activity reduces rotavirus infection." (PMID 27382365, 2016).
tauopathies (2 papers, 2021 to 2022). "As a consequence, we cannot predict the efficacy of chronic PPARγ stimulation on the tauopathy encountered at late stages of AD." (PMID 34522221, 2021). "Thus, to discriminate the two tauopathies, we hereby propose JUN(B,D)HIGH, FOS(L1,L2)HIGH as well as the involvement of DUX4, KLF5, MAX::MYC, PAX6, and PPARG to support the identity of CBD-originated astrocytes." (PMID 35976433, 2022).
temporal lobe epilepsy (2 papers, 2022 to 2023). A localization-related (focal) form of epilepsy characterized by recurrent seizures that arise from foci within the temporal lobe, most commonly from its mesial aspect. "We evaluated the effects of cannabidiol (CBD) on seizures and peroxisome proliferator-activated receptor gamma (PPARγ) levels in an animal model of temporal lobe epilepsy (TLE)." (PMID 35631322, 2022). "Recent evidence also suggests that CBD might work through the transcription factor, peroxisome proliferator-activated receptor gamma (PPARγ), as the anti-seizure effects of CBD was associated with increased hippocampal PPARγ expression in a rat model of temporal lobe epilepsy." (PMID 36701411, 2023).
tendinopathy (2 papers, 2018 to 2020). "We identified a Runx2 inhibitor, AGA, which blocks the osteogenic differentiation of TDSCs from chemically induced tendinopathy, and a PPARγ antagonist, T0070907, that inhibits the adipogenic differentiation of TDSCs from injury-with-overuse tendinopathy." (PMID 32294907, 2020). "However, presently the increase in fat tissue in the tendinopathy and chronic ruptured tendons compared to the acute ruptured tendons was confirmed by the gene expression data, with an increased FABP4 and PPARγ expression in tendinopathy and chronic ruptured tendons." (PMID 29385715, 2018).
testicular cancer (2 papers, 2008 to 2021). A primary or metastatic malignant neoplasm that affects the testis. "In human testicular cancer, PPARγ is induced by its ligands mediating potent antiproliferative effects through differentiation." (PMID 34679887, 2021). "In prostate and testicular cancers, PPARγ constitutes a potent target to treat and prevent these diseases." (PMID 34679887, 2021).
uveal melanoma (2 papers, 2021 to 2023). A melanoma derived from melanocytes of the uveal tract. "Previously, we have shown that PPARγ is expressed in uveal melanoma (UM) which is the most frequent intraocular primary tumor in Caucasian adults." (PMID 34439147, 2021). "Apart from protein–protein interactions and co-expression in multiple cancer types, we exclusively described a prognostic role for PPARγ in uveal melanoma (UM)." (PMID 34439147, 2021).
vulvar carcinoma (2 papers, 2021 to 2022). "Our study proved that the expression of COX-2 and PPARγ and their combination in the tissue of the vulvar carcinoma has a strong impact on survival." (PMID 33802010, 2021). "This study investigates COX-2- and PPARγ- expression in tissues of vulvar carcinomas and their relevance as prognostic factors." (PMID 33802010, 2021). "The prognostic significance of PPARγ in vulvar cancer is clearly different depending on its localization of expression." (PMID 33802010, 2021). "COX-2 and PPARγ together function independent from other clinical pathological parameters as strongly significant prognostic factors for patients with vulvar cancer." (PMID 33802010, 2021). "In the present study, a predictive difference between nuclear expression and cytoplasmic expression of PPARγ in vulvar cancer patients is investigated and described for the first time." (PMID 33802010, 2021). "Therefore, the aim of this study was to investigate COX-2- and PPARγ- expression in tissues of vulvar carcinomas and to analyze their relevance as prognostic factors." (PMID 33802010, 2021). "Nevertheless, we also found that PPARγ can also be stained in the cytoplasm of vulvar carcinoma." (PMID 33802010, 2021). "After demonstrating that COX-2 and PPARγ are prognostic factors for overall and disease-free survival in vulvar cancer, research should continue on further possible pathways linking COX-2 and PPARγ." (PMID 33802010, 2021). "Especially the combined expression of both COX-2 and PPARγ in the cytoplasm is an independent negative prognosticator for vulvar cancer patients." (PMID 33802010, 2021). "Finally, the Cox regression analysis concluded that PPARγ was not an independent factor for disease-free survival in vulvar cancer (p = 0.626)." (PMID 33802010, 2021). "Our group showed negative prognosticators in vulvar cancer patients, such as LDOC1 or combined expression of COX-2 and PPARγ in cytoplasm of vulvar cancer tissue." (PMID 35563052, 2022).
adrenal hypoplasia (1 paper, 2015). "Included in this group were AR, Coup-TFα, Coup-TFβ, dosage-sensitive sex reversal-adrenal hypoplasia congenital critical region on the X chromosome, gene 1 (DAX1), ERα, ERRα, HNF4γ, liver receptor homolog-1 (LRH1), NOR1, NURR1, PPARγ, RARβ, RORα, RORβ, and VDR." (PMID 26244663, 2015).
adrenocortical tumors (1 paper, 2023). "Since the first clinical application of PPARG agonists, thiazolidinediones (TZD) in 1997, there have been various studies exploiting the activation of PPARG pathway in various pathologies, including CD, regulation of steroidogenesis and adrenocortical tumors with varying results." (PMID 38098864, 2023).
alcohol use disorder (1 paper, 2022). "Recently, peroxisome proliferator-activated receptor-gamma (PPARγ) agonism has been shown as a new strategy to address alcohol use disorder (AUD) and possibly to other addictive substances." (PMID 36291651, 2022).
alveolitis (1 paper, 2023). "Early during the inflammatory response and alveolitis, PPARγ promotes TGFβ transcription, leading to massive apoptosis of AECs and development of PF; however, in advanced PF, PPARγ inhibits TGFβ transcription." (PMID 37231189, 2023).
anal carcinoma (1 paper, 2024). "Meantime, prior studies suggested that thiazolidinediones and glucagon-like peptide-1 analogues were connected with cancer risk, which could further validate our findings that PPARG and GLP1R were associated with increased anal carcinoma and cardia cancer risk." (PMID 38504335, 2024).
anemia (1 paper, 2024). A reduction in the number of red blood cells, the amount of hemoglobin, and/or the volume of packed red blood cells. "A recent study demonstrated that HES1 acts in concert with a Fanconi anemia protein, FANCD2 to suppress inflammation-induced PPARg to prevent HSC exhaustion." (PMID 39075526, 2024).
anorexia nervosa (1 paper, 2016). A disorder most often seen in adolescent females characterized by a refusal to maintain a minimally normal body weight, an intense fear of gaining weight, a disturbance in body image, and, in postmenarcheal females, the development of amenorrhea. "Of those nine genes, AKAP6 and NTNG1 were genes associated with anorexia nervosa and the remaining seven (AGT, CD36, CD38, FOXP1, PPARA, PPARG and SELL) were selected for their relationship with T2D." (PMID 27483138, 2016).
Aortic dissection (1 paper, 2024). Aortic dissection refers to a tear in the intimal layer of the aorta causing a separation between the intima and the medial layers of the aorta. "In the context of aortic dissection, there may be interactions and functional associations between VEGFA and PPARG." (PMID 38567101, 2024). "As a transcription factor, PPARG may modulate the expression of VEGFA, thereby influencing angiogenesis and vascular permeability, further impacting the development and progression of aortic dissection." (PMID 38567101, 2024).
aortic valve disease (1 paper, 2022). "Therefore, it is needed to investigate the effect of co-treatment of lipid-lowering drugs and PPARγ agonists in the early aortic valve disease." (PMID 36115863, 2022). "Thus, we propose PPARγ as a key anti-inflammatory regulator in the pre-calcified stage of aortic valve disease." (PMID 36115863, 2022).
aortic valve stenosis (1 paper, 2022). Aortic valve stenosis (AVS) is a condition characterized by narrowing of the heart's aortic valve opening. "Reduced SOD activity levels are either due to low SOD exposure or due to impairment of processes that regulate SOD expression, e.g., peroxisome proliferator-activated receptor gamma or paradoxical reductions in proinflammatory stimuli that occur in late-stage aortic valve stenosis." (PMID 35535358, 2022).
asthenospermia (1 paper, 2023). "It is important to note that only PPARγ from the PPAR family is significantly decreased in asthenospermia patients whose sperm show low motility." (PMID 37992807, 2023).
atopic asthma (1 paper, 2014). An asthma that is characterized by symptoms that are triggered by an allergic reaction caused by inhaled allergens such as dust mite allergen, pet dander, pollen and mold. "In a mouse model of atopic asthma, pharmacologic activation of PPARG reduces the canonical Th2 cytokines IL4 and IL13 and GATA3 protein in lung extracts." (PMID 24426833, 2014).
autoimmune PAP (1 paper, 2018). "Although both statins and PPARγ agonists are available and commonly used, clinical trials will be needed to determine the relative safety and potential efficacy of these pharmacotherapies in patients with autoimmune PAP." (PMID 30087322, 2018).
benign ovarian tumours (1 paper, 2005). "The basal expression of PPARγ in normal ovarian tissues and benign ovarian tumours may have been attributed by the increased immunosensitivity of Western blotting technique compared to immunohistochemistry." (PMID 15583697, 2005).
biliary cirrhosis (1 paper, 2013). "In HSCs from BDL mice developing biliary cirrhosis, PPARγ expression and DNA binding was dramatically reduced, demonstrating that HSC activation is associated with the reductions in PPARγ expression." (PMID 23540496, 2013).
bronchiectasis (1 paper, 2018). Segmental, irreversible dilation of the bronchial tree resulting in the accumulation of secretions which leads to obstruction. "In keeping with the observations made in patients with CF, high airway levels of P. aeruginosa in patients with bronchiectasis are associated with low levels of PPARγ expression, suggesting an intrinsic link with this bacterial species." (PMID 30114278, 2018). "Within patients with bronchiectasis, PPARγ expression did not correlate with either total bacterial load (as measured by 16S qPCR; r = 0.24, p = 0.194) or H. influenzae bacterial load (r = 0.30, p = 0.325)." (PMID 30114278, 2018). "PPARγ gene expression was assessed in bronchoalveolar lavage fluid (BAL) of 35 macrolide naïve non-CF bronchiectasis subjects and compared with that in 20 healthy controls." (PMID 30114278, 2018). "Our aim was to assess the relevance of PPARγ in the context of P. aeruginosa colonisation in non-CF bronchiectasis." (PMID 30114278, 2018). "We examined the expression of PPARγ in the airways of macrolide naïve non-CF bronchiectasis patients who were recruited as part of a prospective randomised controlled trial." (PMID 30114278, 2018). "We assessed PPARγ gene expression in cells derived from the airway fluid of healthy and non-CF bronchiectasis subjects." (PMID 30114278, 2018). "Nonetheless, the data presented here demonstrates for the first time that lower levels of PPARγ are present in the airways of non-CF bronchiectasis subjects, despite an aggressive inflammatory response." (PMID 30114278, 2018). "PPARγ is expressed in low levels in the airways of non-CF bronchiectasis subjects, despite an aggressive inflammatory response." (PMID 30114278, 2018). "Our data suggests reduced levels of PPARγ are also characteristic of the non-CF bronchiectasis airways, despite an aggressive inflammatory response." (PMID 30114278, 2018). "Despite the availability of commercial PPARγ agonists, which might provide clinical benefit, there have been no reported investigations of the role of PPARγ in non-CF bronchiectasis." (PMID 30114278, 2018). "We hypothesised that down-regulation of the anti-inflammatory nuclear transcription regulator peroxisome proliferator-activated receptor gamma (PPARγ in non-CF bronchiectasis subjects may explain why this exuberant neutrophilic inflammation is able to persist unchecked in the inflamed airway." (PMID 30114278, 2018). "PPARγ expression was lower in subjects with non-CF bronchiectasis compared with healthy control subjects (control: 1.00, IQR 0.55–1.44, n = 20 vs. Bronchiectasis: 0.49, IQR 0.12–0.89; n = 35; p<0.001, Mann-Whitney U test)." (PMID 30114278, 2018).
Calcium oxalate nephrolithiasis (1 paper, 2024). The presence of calcium- and oxalate-containing calculi (stones) in the kidneys. "We sought to elucidate the role of imbalanced mitochondrial dynamics in calcium oxalate nephrolithiasis and the ameliorative effect of PPARγ agonist treatment on mitochondrial damage in TECs." (PMID 39325731, 2024). "Overall, we believe that calcium oxalate attachment participates in the activation of TEC apoptosis in calcium oxalate nephrolithiasis by affecting mitochondrial dynamic, which could be rescued with PPARγ activation." (PMID 39325731, 2024). "Given the rescue effects of TR on imbalanced mitochondrial dynamic and apoptosis damage processes in vitro, we intended to subsequently validate the effects of PPARγ agonists on renal damage in calcium oxalate nephrolithiasis within the experimental animal model." (PMID 39325731, 2024).
cardia cancer (1 paper, 2024). A malignant neoplasm involving the cardia of stomach. "Risk of cardia cancer was connected with KCNJ11 (OR = 0.229; 95% CI: 0.059–0.884; P-value = 0.032) and PPARG (OR = 2.813; 95% CI: 1.239–6.388; P-value = 0.013)." (PMID 38504335, 2024).
cerebral palsy (1 paper, 2024). A group of disorders affecting the development of movement and posture, often accompanied by disturbances of sensation, perception, cognition, and behavior. "Additionally, a next-generation sequencing study in 20 patients with cerebral palsy found that 11 patients (55%) had pathogenic or potentially pathogenic variants, including one patient with a mutation in the PGK1 gene, indicating that a disrupted PPARγ network can lead to abnormalities." (PMID 39065726, 2024).
Charcot-Marie-Tooth disease (1 paper, 2024). An inherited degenerative disorder involving the peripheral nerves. "Our findings highlight the critical role of GDAP1 in preserving MCSs and the structural integrity and functional capacity of peripheral nerves and propose PPARγ as a potential drug target for GDAP1-related Charcot-Marie-Tooth disease." (PMID 39801517, 2024). "PPARγ exhibits anti-inflammatory properties and plays a key role in regulating lipid metabolism, which could offer therapeutic benefits in Charcot-Marie-Tooth disease, as neuroinflammation and oxidative stress are known contributors to peripheral nerve degeneration in this condition." (PMID 39801517, 2024).
cholangitis (1 paper, 2010). An acute or chronic inflammatory process affecting the biliary tract. "Moreover, a negative regulator of intracellular TLR signaling, peroxisome proliferator-activated receptor-γ (PPARγ), is involved in the pathogenesis of cholangitis." (PMID 20798866, 2010).
cocaine addiction (1 paper, 2023). "BCP dual activation of PPARα and PPARγ, observed in our in vitro experiments and previously shown in cocaine addiction studies performed in vivo, highlights the possibility that BCP might behave as a dual PPARα/γ agonist like saroglitazar." (PMID 37047034, 2023).
cocaine use disorder (1 paper, 2020). A substance-related disorder that involves the recurring use of cocaine despite negative consequences. "Our results support recent findings suggesting the involvement of PPARγ in cocaine use disorder." (PMID 32895370, 2020).
Corneal opacity (1 paper, 2009). A reduction of corneal clarity. "This in vitro study demonstrated the anti-fibrotic effect of pioglitazone, suggesting that activation of PPARγ may be a new approach for the treatment of corneal opacity and scar formation in the corneal wound healing process." (PMID 19936025, 2009).
cutaneous leishmaniasis (1 paper, 2021). Leishmaniasis affecting the skin. "In visceral and cutaneous leishmaniasis, several studies have demonstrated that the activation of macrophage PPARγ promotes disease progression, and its inhibition delays lesion development." (PMID 34281214, 2021).
cystitis (1 paper, 2023). Inflammation of the urinary bladder. "Based on results from other studies, showing that CB2, but not CB1, activation is involved in attenuation of bladder inflammation and the severity of experimental cystitis, we speculated that CB2 and PPARγ are the most probable targets of CBD in SV-HUC1 cells." (PMID 36902479, 2023).
diabetic encephalopathy (1 paper, 2025). A brain disease that is characterized by functional impairment of cognition, cerebral signal conduction, neurotransmission and synaptic plasticity, and underlying structural pathology associated with diabetes. "PPARG agonists, especially pioglitazone, show protective actions in experimental models of AD and diabetic encephalopathy." (PMID 41282094, 2025).
dysautonomia (1 paper, 2020). An acute or chronic disorder, affecting the sympathetic or parasympathetic nervous system. "The present post mortem study in a rhesus monkey model of PD cardiac dysautonomia aimed to validate in vivo cardiac PET markers of sympathetic innervation, oxidative stress and inflammation and evaluate PPARγ target engagement by pioglitazone." (PMID 31910209, 2020).